DSN1 (DSN1 component of MIS12 kinetochore complex)
Description:
Part of the MIS12 complex which is required for normal chromosome alignment and segregation and kinetochore formation during mitosis.
Synonyms: C20orf172; MIS13; dJ469A13.2; KNL3; hKNL-3
Tractability: Antibody: its Gene Ontology location is reachable by antibodies, with high confidence. PROTAC: UniProt records ubiquitination sites on it; ubiquitination databases record sites on it; its protein half-life has been measured.
Gene: Protein-coding gene on chromosome 20 (36,751,791 to 36,774,298, reverse strand). Ensembl gene ENSG00000149636.
Subcellular location: Nucleus; Chromosome, centromere, kinetochore
Subcellular location (Human Protein Atlas): Nucleoplasm; Cytosol; Kinetochore; Nuclear bodies; Nucleoli fibrillar center
Pathways (Reactome):
Cell Cycle: Amplification of signal from unattached kinetochores via a MAD2 inhibitory signal; EML4 and NUDC in mitotic spindle formation; Mitotic Prometaphase; Resolution of Sister Chromatid Cohesion; Separation of Sister Chromatids
Immune System: Neutrophil degranulation
Signal Transduction: RHO GTPases Activate Formins
Gene Ontology:
Molecular function: protein binding
Biological process: attachment of spindle microtubules to kinetochore; cell division; chromosome segregation
Cellular component: fibrillar center; kinetochore; MIS12/MIND type complex; nuclear body; nucleoplasm; nucleus; outer kinetochore; azurophil granule lumen; cytosol; extracellular region; spindle pole
Genetic constraint (gnomAD): Loss-of-function variants: 31 observed, 49.42 expected, observed/expected ratio (o/e) 0.63, 90% interval 0.47 to 0.85. The upper end of that interval is the gene's LOEUF score, 0.85, which puts it in group 3 of 6, group 1 being the genes least tolerant of losing a copy. Missense variants: 391 observed, 433.72 expected, observed/expected ratio (o/e) 0.9, 90% interval 0.83 to 0.98. Synonymous variants: 134 observed, 149.98 expected, observed/expected ratio (o/e) 0.89, 90% interval 0.78 to 1.03.
Homologues: Orthologues: chimpanzee DSN1 (99% identical), macaque DSN1 (94% identical), dog DSN1 (80% identical), pig DSN1 (79% identical), rabbit DSN1 (77% identical), guinea pig DSN1 (74% identical), mouse Dsn1 (69% identical), rat Dsn1 (68% identical), tropical clawed frog dsn1 (30% identical), zebrafish dsn1 (19% identical).
Diseases named in the same sentence as DSN1 in open-access papers:
DSN1 is named in the same sentence as 19 diseases in open-access papers, as found by Europe PMC text mining. Sharing a sentence is not in itself a finding about the gene and the disease. The quoted sentences say what the papers report.
gastric cancer (5 papers, 2021 to 2025). A primary or metastatic malignant neoplasm involving the stomach. "ESRRA regulates the CD/CDK1/CyclinB1 pathway through DSN1 and promotes the development of gastric cancer." (PMID 38189879, 2024).
breast carcinoma (4 papers, 2015 to 2026). "Cellular experiments confirmed that DSN1 promotes breast cancer proliferation by affecting cell cycle pathways, involving key molecules such as CCNB1, CCND1, CKD1, CDK4, and CDK6." (PMID 41640445, 2026). "While ESRRA is recognized for its role in various cancers, including breast cancer 46, glioma 47, and gallbladder cancer 48, its regulation of DSN1 provides a mechanistic link between this transcription factor and the cell cycle machinery." (PMID 40535813, 2025). "Detailed genomic analyses of these components coupled with in vitro experiments resulted in the identification of BRF2 and DSN1 amplification and HER2 I767M somatic mutation as potential novel breast cancer driver genetic events." (PMID 25994018, 2015). "Furthermore, we examined how DSN1 affects the growth of breast cancer cells by conducting CCK8 and colony formation tests." (PMID 41640445, 2026). "In addition, we identified and functionally validated alternative driver genetic alterations restricted to the HER2-negative component of HER2 heterogeneous breast cancers, including BRF2 and DSN1 amplification, and a HER2 somatic mutation." (PMID 25994018, 2015). "Hence, we sought to define whether BRF2 and DSN1 would have oncogenic properties in in vitro models of breast cancer." (PMID 25994018, 2015). "In vitro experiments provided functional evidence to suggest that BRF2 and DSN1 overexpression/amplification, and the HER2 I767M mutation may be alterations that compensate for the lack of HER2 amplification in the HER2-negative components of HER2 heterogeneous breast cancers." (PMID 25994018, 2015). "From this list of genes, we focused on BRF2 and DSN1, given the lack of direct functional evidence to support a potential oncogenic role of the amplification of these genes in breast cancer." (PMID 25994018, 2015).
colorectal cancer (4 papers, 2021 to 2025). A primary or metastatic malignant neoplasm that affects the colon or rectum. "In colorectal cancer, DSN1 affects cell cycle progression and is tightly associated with clinical-pathological features." (PMID 35509101, 2022). "Similarly, in the research focusing on DSN1 expression and colorectal cancer progression, evidences also showed that down-regulating of DSN1 favor cyclin B1 expression and increase G2M arrest, which is in accordance with the research conclusion drawn above." (PMID 34131395, 2021).
hepatocellular carcinoma (4 papers, 2019 to 2025). A malignant tumor that arises from hepatocytes. "Genes, such as MCM3, MCM5, MCM7, and DSN1, are associated with the pathogenesis of various cancers, such as salivary gland cancer, cervical cancer, and hepatocellular carcinoma, through regulation of cell cycle, but these genes may be involved in progression of BRCA." (PMID 31311202, 2019). "RBM45 downregulation suppresses hepatocellular carcinoma proliferation, while SRSF9 stabilizes oncogenic transcripts like DSN1, which correlates with lymph node metastasis and an advanced stage of CRC." (PMID 40724932, 2025).
colorectal adenoma (2 papers, 2016 to 2024). An adenoma that arises from the colon or rectum. "Related reports have revealed that DSN1, a carcinogen, is highly expressed and correlated with the proliferation of colorectal adenomas." (PMID 39555702, 2024).
glioma (2 papers, 2024 to 2025). A benign or malignant brain and spinal cord tumor that arises from glial cells (astrocytes, oligodendrocytes, ependymal cells). "DSN1 or its methylation has diagnostic value for the prognosis of glioma, and may become a new biological target of anti-tumor immunotherapy." (PMID 39555702, 2024). "This provides further evidence that the hypermethylation of CpG sites reduces the expression of DSN1, which may affect the pathological progression of gliomas." (PMID 39555702, 2024). "For example, in most glioma and Pancreatic adenocarcinoma (PAAD) datasets, DSN1 was predominantly expressed in malignant cells as well as other cell types." (PMID 40535813, 2025). "Therefore, this study used three datasets from the The Cancer Genome Atlas (TCGA), The Chinese Glioma Genome Atlas (CGGA) microarray, and CGGA RNA-Seq databases to reveal the potential relationship between the expression of DSN1 and patient survival in terms of both molecular and clinical aspects." (PMID 39555702, 2024).
adenoma (1 paper, 2016). A neoplasm arising from the epithelium. "The moderate accuracy of SKA3 and DSN1 in discriminating carcinoma from polyp might be due to the inclusion of high-risk adenomas in the polyp groups." (PMID 27329586, 2016). "We confirmed that Aurora A, SKA3, and DSN1 proteins were up-regulated in the adenoma and carcinoma tissues." (PMID 27329586, 2016). "Among the identified candidate genes, AURKA, SKA3, and DSN1, which are involved in cell cycle transition, cell growth, and proliferation, were progressively up-regulated in paired non-neoplastic colon tissues, adenomas, and carcinomas." (PMID 27329586, 2016).
low grade glioma (1 paper, 2024). A grade I or grade II glioma arising from the central nervous system. "However, the effect of DSN1 or its methylation on the prognosis, molecular characteristics, and immune cell infiltration of low-grade glioma (LGG) has not yet been studied." (PMID 39555702, 2024).
melanoma (1 paper, 2025). A malignant, usually aggressive tumor composed of atypical, neoplastic melanocytes. "The analysis revealed that patients with high DSN1 expression had a longer overall survival (OS) in melanoma, while a shorter OS was observed in BLCA." (PMID 40535813, 2025). "This could, in part, explain the higher response rates to immunotherapy observed in DSN1-high patients with melanoma and BLCA." (PMID 40535813, 2025). "Additionally, patients with high DSN1 expression in melanoma and BLCA exhibited higher response rates to immunotherapy." (PMID 40535813, 2025).
cancer (10 papers, 2015 to 2025). A tumor composed of atypical neoplastic, often pleomorphic cells that invade other tissues. "While high DSN1 expression in many cancers correlates negatively with immune and stromal scores, the underlying mechanisms appear to be cancer-type specific." (PMID 40535813, 2025). "DSN1 expression is associated with proliferation and invasion (T stage) in several cancers, including HNSC, LIHC, LUAD, PRAD, TGCT, and THCA." (PMID 40535813, 2025). "The results demonstrated significant differences in alteration frequencies of DSN1 among different cancer types, with COAD exhibiting the highest mutation frequency (approximately 9.26%), followed by UCEC and ESCA." (PMID 40535813, 2025). "Across multiple cancer types, high DSN1 expression was significantly associated with the activation of key cell cycle-related pathways, suggesting that DSN1 may promote tumor cell proliferation by influencing these pathways." (PMID 40535813, 2025). "Furthermore, we used the cBioPortal database to investigate the mutation types and alteration frequency of DSN1 across pan-cancer." (PMID 40535813, 2025). "Moreover, TCGA phenotype data analysis indicated that DSN1 expression was associated with several clinical features in cancer patients." (PMID 40535813, 2025). "The overexpression of DSN1 showed a significant correlation with either poor or favorable prognosis, depending on the cancer type." (PMID 40535813, 2025). "With data from the TCGA and GTEx databases, we found that DSN1 expression was significantly elevated in most cancer samples compared to normal samples." (PMID 40535813, 2025). "Correlation analysis across various cancer types indicated that methylation at most TSS-proximal sites negatively correlated with DSN1 expression, suggesting a regulatory role in gene suppression." (PMID 40535813, 2025). "Our study provides a comprehensive pan-cancer analysis of DSN1, revealing its multifaceted roles in tumorigenesis and its context-dependent impact on prognosis and the tumor immune microenvironment." (PMID 40535813, 2025). "The relationship between DSN1 and the tumor immune microenvironment exhibited striking variations across different cancer types." (PMID 40535813, 2025). "While the crucial role of DSN1 in maintaining genomic stability through proper chromosome segregation is established 37,43, its pan-cancer implications remain under investigation." (PMID 40535813, 2025). "To investigate the immune-related role of DSN1 across various cancers, we initially assessed the relationship between DSN1 expression and immune and stromal scores across 32 cancer types." (PMID 40535813, 2025). "The heterogeneity in DSN1's interaction with the immune landscape underscores the necessity for a context-dependent understanding of its immunomodulatory role in different cancers." (PMID 40535813, 2025). "In cancers where DSN1 overexpression drives aggressive proliferation and genomic instability (e.g., BRCA LIHC), its association with poor outcomes is consistent with its role in promoting uncontrolled cell division." (PMID 40535813, 2025). "The distinct immune landscape of LUSC, where DSN1 is negatively correlated with many immune-related genes, further emphasizes this cancer-type specificity." (PMID 40535813, 2025). "While DSN1 is predominantly studied in cancer, emerging evidence suggests its functional relevance in non-cancerous contexts." (PMID 40535813, 2025). "The findings revealed a strong correlation between DSN1 expression and various anticancer drugs across multiple cancer types." (PMID 40535813, 2025). "Immune checkpoint inhibitor (ICI)-based immunotherapy has emerged as a highly promising strategy in cancer treatment 50, and DSN1 showed a potential as a biomarker for immunotherapy and drug sensitivity." (PMID 40535813, 2025).
cancer (continued). "Conversely, in most cancer types, elevated DSN1 expression was negatively correlated with CD4+ T cell recruitment (step 4), macrophage recruitment (step 4), and Th17 cell recruitment (step 4)." (PMID 40535813, 2025). "This study delves into the pan-cancer landscape of DSN1, examining its expression dynamics, its contribution to cancer biology, and its clinical implications across a spectrum of human cancers." (PMID 40535813, 2025). "The observed upregulation of DSN1 in cancer is likely driven by a combination of genomic and epigenomic alterations." (PMID 40535813, 2025). "While the role of DSN1 in certain malignancies is partially understood, comprehensive research on its role across pan-cancer remains limited." (PMID 40535813, 2025). "Our findings, in conjunction with previous research, demonstrate that DSN1 is frequently overexpressed in a wide array of cancers." (PMID 40535813, 2025). "This study provides the first comprehensive pan-cancer analysis of DSN1, revealing its diverse roles in tumorigenesis and progression, and establishing its potential as a promising biomarker for immunotherapy and drug sensitivity prediction." (PMID 40535813, 2025). "We assessed the relationship between DSN1 expression and patient prognosis, exploring its potential as a pan-cancer biomarker." (PMID 40535813, 2025). "Our findings indicated that high DSN1 levels were positively correlated with neutrophil recruitment (step 4), Th2 cell recruitment (step 4), and cancer cell killing (step 7)." (PMID 40535813, 2025). "We performed a pan-cancer Gene Set Enrichment Analysis (GSEA) to compare differentially expressed genes (DGEs) between high and low DSN1 expression groups across various cancer types to investigate the influence of DSN1 in cancer development." (PMID 40535813, 2025). "Lastly, we explored the potential uses of DSN1 in cancer treatment by integrating predictions for drug sensitivity and immune therapy response." (PMID 40535813, 2025). "In nearly all cancer types, high DSN1 expression was significantly negatively correlated with Tozasertib and Sepantronium (indicating high drug sensitivity) and significantly positively correlated with Selumetinib (indicating high drug resistance)." (PMID 40535813, 2025). "Notably, cancers such as COAD, LUAD, and UCEC exhibited high mutation and amplification frequencies in the DSN1-high group." (PMID 40535813, 2025). "Notably, methylation at cg19753867 revealed a markedly positive correlation with DSN1 expression in nearly 40% of cancer types, including BLCA, BRCA, and others." (PMID 40535813, 2025). "However, the contrasting prognostic implications of high DSN1 expression in these two cancers during immunotherapy—favorable in BLCA and unfavorable in SKCM—highlight the critical influence of the specific tumor immune microenvironment." (PMID 40535813, 2025). "The prognostic significance of DSN1 exhibits marked variability across different cancer types." (PMID 40535813, 2025). "Additionally, elevated DSN1 level were identified as a risk factor for DFI and PFI in various cancer types." (PMID 40535813, 2025). "Additionally, data from twelve independent studies in the GEO database 31,32 consistently confirmed that DSN1 was upregulated in most cancers types." (PMID 40535813, 2025). "Furthermore, IHC images in the HPA database 19 corroborated these findings, showing higher DSN1 protein signals in the cancer tissues compared to the normal counterparts." (PMID 40535813, 2025). "Our findings revealed that DSN1 exhibited elevated expression levels in both malignant and immune cells, with particularly notable expression in proliferating T cells (Tprolif) in many cancer types." (PMID 40535813, 2025). "Furthermore, we explored the correlation between DSN1 levels and immune cell infiltration across multiple cancer types." (PMID 40535813, 2025).
cancer (continued). "While these findings are promising, they require validation through in vitro and in vivo experiments with more clinical data, as well as further investigation with larger clinical datasets to confirm the potential differential roles of DSN1 across various cancer types." (PMID 40535813, 2025). "Additionally, DSN1 expression exhibited a positive correlation with MSI scores in many cancer types including ACC, BLCA, BRCA, CESC, ESCA, and others." (PMID 40535813, 2025). "DSN1 promoted the activation of multiple cancer-related pathways, such as the cell cycle." (PMID 39555702, 2024). "DSN1 has been previously found to be positively correlated with various cancers." (PMID 39555702, 2024). "Additionally, the PARADIGM features corresponding to the genes CDC25B and DSN1 have higher activity in tumours with high NCS across many cancers." (PMID 35326573, 2022). "Additional studies involving other types of cancer may be undertaken to explore whether the m6A-related manner through which SRSF9 targets DSN1 could be broadly applied as a potential basis for cancer therapy." (PMID 35509101, 2022). "However, the notable positive correlation with Th2 cell infiltration across various cancers suggests another potential mechanism by which DSN1 may promote tumor progression." (PMID 40535813, 2025). "What's more, deregulated DSN1 may contribute to uncontrolled cell cycle and cancer development." (PMID 34131395, 2021). "To elucidate the role of DSN1 expression in pan-cancer immunotherapy, we utilized the TIP database to obtain immune activity ratings for the cancer immune cycle." (PMID 40535813, 2025). "Our analysis reveals that gene amplification is a significant contributor, particularly in cancers like COAD, ESCA, OV, and STAD, where high frequencies of DSN1 amplification were observed." (PMID 40535813, 2025). "The positive correlation between DSN1 expression and TMB, as well as MSI, in a substantial number of cancers suggests that DSN1-high tumors might be more immunogenic, potentially due to increased neoantigen presentation resulting from genomic instability." (PMID 40535813, 2025). "Furthermore, DSN1 expression was positively correlated with DNA methylation, TMB, and MSI in most cancers." (PMID 40535813, 2025). "To assess the predictive effect of DSN1 across pan-cancer types, we employed univariate and multivariate Cox regression analyses, which revealed that DSN1 expression, along with age, gender, TNM T stage, TNM M stage, tumor stage, recurrence, and cancer type, independently predicted patient survival." (PMID 40535813, 2025). "Notably, DSN1 expression showed a negative correlation with many immune-related genes in LUSC, which is different from many other cancer types." (PMID 40535813, 2025).